NEAT1 (nuclear paraspeckle assembly transcript 1)
Diseases named in the same sentence as NEAT1 in open-access papers (continued):
Sharing a sentence is not in itself a finding about the gene and the disease.
cancer (continued). "Although dysregulation of certain lncRNAs has been demonstrated in chemo-resistant cancers, the functional mechanisms of lncRNA NEAT1 shuttled by ADSC-EVs in PCa remain undetermined." (PMID 36762032, 2023). "Blast cells from B/My MPAL MRD + patients overexpressed genes such as NEAT1 and SOX4 that are associated with cancer development and pan-cancer poor outcome." (PMID 37845689, 2023). "We found that NEAT1 promotes intracellular glutamine metabolism and decreases apoptosis in FLSs-RA, consistent with the role of NEAT1 in cancer." (PMID 36050752, 2022). "Improving detection of specific NEAT1 isoforms is crucial in understanding the tumour-promoting vs. the tumour-protective roles of NEAT1 in cancer." (PMID 36139550, 2022). "Overexpression of the short isoform NEAT1 resulted in increased cancer cell growth and rescued the ALYREF knock-down phenotype." (PMID 35776213, 2022). "Lysine-specific demethylase 5A (KDM5A) which is participated in human cancer has been inhibited through binding of NEAT1 to the E2F transcription factor 1 (E2F1) protein." (PMID 35676702, 2022). "lncRNA NEAT1 has recently been identified as a carcinogenic regulator of multiple cancers; however, the role of NEAT1 on PCa is still poorly understood." (PMID 35237319, 2022). "In a sample of 179 BC patients, abnormal NEAT1 activity influenced chemoresistance and cancer cell stemness, and it has been expressed 6.86 times greater in BC patients than that in 192 controls." (PMID 36212140, 2022). "The m6A marks are placed by the RNA methyltransferase 3 (METTL3) and stabilise NEAT1 transcripts in various cancer cells, including renal cell carcinoma and chronic myeloid leukaemia." (PMID 35457249, 2022). "Approaches which have been able to sustain the expression of NEAT1 after exposure to the anti-cancer drug have been successful in attenuating some adverse cardiovascular effects." (PMID 35246252, 2022). "The long noncoding RNA (lncRNA) nuclear enriched abundant transcript 1 (NEAT1), which was reported to promote proliferation and migration in cancer progression, was significantly increased in ductal nuclei grouped in cluster 4 in the combined model." (PMID 35819843, 2022). "PANDAR, HOTAIR, HULC, H19, MALAT1, XIST, and NEAT1 have been considered as the oncogenes in various cancers, which can act as a “sponge” and compete for the binding of miRNAs of other genes." (PMID 36262350, 2022). "Current approaches to interfere with NEAT1 function in cancer cells include the application of antisense oligonucleotides (ASOs) that impair NEAT1 synthesis." (PMID 35457249, 2022). "As one of the best-studied long noncoding RNAs, nuclear paraspeckle assembly transcript 1 (NEAT1) plays a pivotal role in the progression of cancers." (PMID 36011001, 2022). "In those cancers, NEAT1 plays a pro-proliferative role and promotes the progression of cancer by upregulating the expression of some oncogenes or downregulating the expression of some tumor suppressor genes." (PMID 36011001, 2022). "The second lncRNA identified in our study, NEAT1, is known for its involvement in tumorigenesis, mainly acting as a competing endogenous RNA for tumor-suppressor miRNAs, thus, inducing cancer development." (PMID 35203705, 2022). "NEAT1 can be elevated via transcriptional activation or stability alteration in cancers changing the aggressive phenotype of cancer cells." (PMID 36011001, 2022). "Three well-known upstream long non-coding-RNAs (lncRNAs); MALAT1, NORAD, and NEAT1 target miR-202 and inhibit its tumor suppressive function thus fueling cancer progression." (PMID 35682549, 2022). "Under certain transcriptionally active conditions, NEAT1 is redistributed in the nucleus and recruited to the promoters of several cancer-related target genes to induce an active chromatin state for transcription." (PMID 36171622, 2022).
cancer (continued). "The NEAT1 gene exhibits characteristics of cancer drivers since it initiates and progresses tumors, and its frequent dysregulation in cancer is correlated with metastasis, recurrence rate, and survival." (PMID 35676702, 2022). "Recent studies have shown that NEAT1 is upregulated and acts as a tumour promoter gene in various cancers." (PMID 36434587, 2022). "NEAT1 also plays different roles in cancer development and both NEAT1 isoforms have been proposed as cancer biomarkers, with NEAT1_2 considered a tumor suppressor and NEAT1_1 considered to be oncogenic." (PMID 36279270, 2022). "qRT-PCR assay confirmed that stable transfection of sh-NEAT1 efficiently silenced NEAT1 expression in the cancer cells." (PMID 35635748, 2022). "The lncRNA NEAT1 has been observed to have increased expression levels in multiple cancers, including colorectal, lung, esophageal, and liver cancers, and has also been recognized as a regulator of cardiovascular function." (PMID 35246252, 2022). "Based on the studies demonstrating the roles of NEAT1 in regulating cancer response to the ferroptosis inducer, erastin, it is plausible that by the co-evaluation of NEAT1 and miR-362-3p expression, one can predict the tumor response to erastin." (PMID 35625948, 2022). "MALAT1, HOTAIR, H19, HOTTIP, ANRIL, and NEAT1 are among the most famous lncRNAs which have been mostly studied in many types of cancer exhibiting dysregulation in cancer cells, tissues and body fluids of affected patients." (PMID 35281110, 2022). "Nuclear Paraspeckle Assembly Transcript 1 (NEAT1) is commonly considered an oncogene in various cancers." (PMID 36262350, 2022). "Then we explore the interaction between NEAT1 and other molecules and analyze the impact of this interaction on cancer progression." (PMID 36011001, 2022). "Nuclear paraspeckle assembly transcript 1 (NEAT1) is a lncRNA that is dysregulated in various human cancers." (PMID 35782387, 2022). "This is the most common mechanism identified by researchers who have attempted to elucidate the functions of NEAT1 in cancer diseases." (PMID 36011001, 2022). "NEAT1 participates in cancer progression and therapeutic response under various conditions, and it seems to be an ideal prognostic marker for assessing hypoxic tumors due to its tumor-promoting role under hypoxia." (PMID 35625948, 2022). "Both MALAT1 and NEAT1, significantly overexpressed in many types of cancer have been identified as regulators in several biological process." (PMID 35814429, 2022). "In summary, strategies based on the downregulation of NEAT1, using for example targeted antisense oligonucleotide (ASO) to block NEAT1 polyadenylation, can open up new avenues in cancer treatment." (PMID 36612180, 2022). "It was reported that the nuclear paraspeckle assembly transcript 1 (NEAT1, a long non-coding RNA) was regarded as a novel target for diagnosis and therapy in human tumors, and higher NEAT1 expression was together with worse survival in cancer patients." (PMID 35910359, 2022). "The long non-coding RNA nuclear paraspeckle assembly transcript 1 (NEAT1), which is frequently overexpressed in diverse human tumors, is correlated with worse survival rate in cancer patients." (PMID 35313796, 2022). "Nuclear enriched abundant transcript 1 (NEAT1) is a novel lncRNA that participated in a variety of cancers, such as breast, gastric, and lung." (PMID 35676702, 2022). "Computational prediction by the non-coding RNA online service starBase 2.0 showed that miRNA-338-3p, which has been reported to be negatively correlated with various cancers, contains a binding site for NEAT1." (PMID 36050752, 2022). "Intriguingly, NEAT1 concomitantly increased the cancer stemness of TNBC cells and upregulated the expression of BMI1, OCT4, and SOX2." (PMID 35054896, 2022). "Stability alterations can ultimately affect the expression level of NEAT1 transcripts, thereby regulating cancer progression." (PMID 36011001, 2022).
cancer (continued). "As an essential component of nuclear paraspeckles, NEAT1 was reported to contribute to a cancer-favorable transcriptional program." (PMID 36171622, 2022). "As an important diagnostic and therapeutic marker, further elucidation of the mechanisms of NEAT1 in cancer progression will undoubtedly benefit clinical work." (PMID 36011001, 2022). "Nevertheless, it is likely that the overexpression of NEAT1 in cancer cells is a consequence of both HuR overexpression and miR-124-3p silencing." (PMID 35884580, 2022). "NEAT1 has previously been shown to be upregulated in several cancer entities, commonly exerting the function of a competing endogenous RNA (ceRNA) and possibly many other functions." (PMID 35776213, 2022). "Bioinformatics analysis predicted that miR-338-3p, which is reported to be frequently downregulated in cancer, is a target of NEAT1." (PMID 36050752, 2022). "As ALYREF has been previously proposed as an RNA-binding protein and the long noncoding RNA NEAT1 has been involved in the growth and cancer stemness of TNBC, we decided to further decipher a possible link between these two molecules." (PMID 35776213, 2022). "We further delineate the applicability of HyPro labeling as a potentially powerful tool to investigate the molecular principles that contribute to the deregulation of NEAT1 transcripts in cancer and promote NEAT1-dependent tumourigenesis." (PMID 35457249, 2022). "Although a little study displayed the anti-cancer role of NEAT1 in CRC, a flood of investigations have still been verified its oncogenic role especially acting as ceRNA to regulate microRNAs." (PMID 36262350, 2022). "Only a few studies have explored the functions of NEAT1 in exosomes; therefore, the detailed mechanisms of NEAT1 in cancers remain relatively ambiguous." (PMID 36011001, 2022). "High expression of NEAT1 was demonstrated to be associated with clinicopathological significance of CRC, including poor prognosis, TNM stage, low survival, and high cancer recurrence." (PMID 35676702, 2022). "NEAT1 is frequently upregulated in cancer where exhibits an oncogenic role mainly by sponging tumor suppressive miRNAs, upregulating, in turn, oncogene expression." (PMID 35814429, 2022). "Recently, NEAT1 has been reported to act as a ceRNA to regulate the expression of downstream genes by sponging miRNAs in malignant tumors." (PMID 35425712, 2022). "Herein, we review the molecular function of NEAT1 in cancer progression, and explain how NEAT1 interacts with RNAs, proteins, and DNA promoter regions to upregulate tumorigenic factors." (PMID 36011001, 2022). "NEAT1, a 3.2 kb lncRNA located in human chromosome 11, plays vital roles in multiple human diseases and serves as a tumor-promoting lncRNA in multiple cancers, including TC." (PMID 35635748, 2022). "In contrast, some transcription factors can inhibit the expression of NEAT1 in cancer cells and immune cells." (PMID 36011001, 2022). "Nuclear-enriched abundant transcript 1 (NEAT1) is one of the most well-studied long non-coding RNAs (lncRNAs) in multiple human carcinoma." (PMID 35687898, 2022). "The lncRNA NEAT1 is involved in human cancers and has been reported to facilitate the migration, invasion, and proliferation of melanoma cells by regulating miR-495-3p and E2F3." (PMID 34414852, 2021). "As our understanding of the role of NEAT1 during tumorigenesis improves, its therapeutic potential as a biomarker and/or target for cancer also becomes clearer." (PMID 34512157, 2021). "Several studies have proved that NEAT1 can regulate c-met via ceRNA mechanism in different cancer types." (PMID 34222227, 2021). "We utilized a lncRNA array dataset (GSE81034) to analyze the expression of well-known, cancer metastasis-associated lncRNAs (i.e., MALAT-1, NEAT-1, HOTAIR, and HOXA11-AS) in the five cell lines by comparing exosomal RNA versus total RNA." (PMID 33514011, 2021).
cancer (continued). "We first analyzed, by ddPCR expression of several cancer-associated lncRNAs (MALAT1, NEAT1, HOTAIR, H19, PVT1, MEG3) in both FNAs and surgical specimens and selected MALAT1, HOTAIR, and PVT1 as cancer biomarkers." (PMID 33030666, 2021). "We also summarize and discuss the feedback roles of NEAT1/miRNA/target network in the progression of various cancers." (PMID 34512157, 2021). "In particular, we analyzed, by Droplet Digital PCR (ddPCR), six cancer-associated lncRNAs (MALAT1, NEAT1, HOTAIR, H19, PVT1, MEG3) in both FNAs and surgical tissues." (PMID 33030666, 2021). "The other lincRNAs, LINC01133 displayed specific expression in primary cancer cells, while NEAT1 was abundant in most of the cell components of both primary and metastatic PDAC tumors." (PMID 34055623, 2021). "The aberrant expression of lincRNA nuclear paraspeckle assembly transcript 1 (NEAT1) in different cancers has been widely described." (PMID 34204634, 2021). "ITGA5 was subsequently identified to interact with the NEAT1/miR-128-3p axis, and NEAT1 safeguarded the cancer-promoting effects of ITGA5 by binding to miR-128-3p competitively." (PMID 34263426, 2021). "Excessive NEAT1 expression plays a critical role in growth and resistance and is positively correlated with unfavorable survival in many cancers." (PMID 34769497, 2021). "The nuclear paraspeckle assembly transcript 1 (NEAT1) is a long non-coding RNA (lncRNA) that is upregulated in a variety of human cancer types." (PMID 34512157, 2021). "Previous studies have reported the association of the serum expression of NEAT1 and MALAT1 with several types of cancer." (PMID 33670447, 2021). "NEAT1 regulates cell behaviors, such as proliferation, apoptosis, and invasion to accelerate cancer growth and metastasis." (PMID 34972503, 2021). "In OC, NEAT1 promotes cancer cell proliferation, invasion, migration, EMT, and angiogenesis by regulating the expression of a wide variety of miRNAs and associated pathways." (PMID 34885213, 2021). "Increasing evidence has shown that the elevation of NEAT1 in cancer cells promotes cell growth, migration, and invasion and inhibits cell apoptosis." (PMID 34512157, 2021). "NEAT1 has been identified as a cancer driver, playing a role in tumor initiation and progression, and its expression was found deregulated in several cancers." (PMID 35008626, 2021). "It is reported that NEAT1 contributes development and progression of cancer by sponging miRNAs 18, 20-22." (PMID 34405022, 2021). "Abnormal NEAT1 activity affected chemoresistance and cancer cell stemness in a cohort of 179 BC patients and it was expressed 6.86 times more in BC patients than in 192 controls." (PMID 33807045, 2021). "While lncRNA H19 expression in plasma samples correlated with expression of its target miR-675 in both healthy and cancer-afflicted patients, the expression of NEAT1 and its target miR-204 correlated only in HER2+ patient plasma samples." (PMID 33807045, 2021). "NEAT1, a cancer lncRNA, controls 13.3% of genes in the PI3K‐AKT signalling pathway by interacting with distal regulatory elements." (PMID 34296520, 2021). "NEAT1 is overexpressed in luminal A, luminal B, HER2+, and basal-like tumors, and high NEAT1 expression is related to poor prognosis and short overall survival in human cancers." (PMID 33820555, 2021). "NEAT1 is frequently overexpressed in human tumors and proposed as a novel target for human cancer therapy and diagnosis by sponging miRNAs." (PMID 34899268, 2021). "Considering the key role of cancer cell hyperproliferation in tumor growth and cancer progression, the effects of silencing NEAT1 on tumor growth upon PDT treatment were subsequently investigated." (PMID 34395239, 2021). "Aberrant expression of MALAT1 and NEAT1 were reported in several types of cancer as hepatocellular carcinoma, pancreatic cancer, ovarian cancer, and colorectal cancer." (PMID 33670447, 2021).
cancer (continued). "LncRNA nuclear paraspeckle assembly transcript 1 (NEAT1) has been reported to be dysregulated in many human cancers and contribute to cancer development 17-21." (PMID 34405022, 2021). "With respect to non-coding RNAs in the networks, NEAT1 has been proven to act as an oncogene in multiple cancers by binding to various miRNAs." (PMID 34051854, 2021). "The nuclear-enriched abundant tran-script 1(NEAT1) acts as a long non-coding RNA(ncRNA) has high expression in a variety of cancer types." (PMID 34899855, 2021). "We also discuss the potential clinical applications of NEAT1-mediated ceRNA networks in overcoming chemo- and radioresistance in cancer treatment." (PMID 34512157, 2021). "Three thyroid-specific genes (TG, TPO, and NIS), six cancer-associated lncRNAs (MALAT1, NEAT1, HOTAIR, H19, PVT1, MEG3), and two housekeeping genes (GAPDH and P0) were analyzed using Droplet Digital PCR (ddPCR)." (PMID 33030666, 2021). "Given the role of NEAT1 in cancer, several studies have been trying to unravel the molecular mechanisms regulating its expression and its targets." (PMID 35008626, 2021). "According to The Cancer Genome Atlas (TCGA) database, lncRNA-nuclear paraspeckle assembly transcript 1 (lncRNA-NEAT1) is upregulated or downregulated depending on the cancer types, implying that its role in cancer is cellular context-dependent." (PMID 33435156, 2021). "Overall, this review summarizes and discusses the roles of the NEAT1-miRNA-target axis in the progression of various cancers and provides insight into its potential clinical utility in cancer treatment." (PMID 34512157, 2021). "The NEAT1–MET axis was identified as gain interaction in our pan-cancer core component, suggesting that the competitive relation between NEAT1 and MET happened in cancer environment." (PMID 34222227, 2021). "It therefore highlights that NEAT1 is of relevant research interest and its role in therapeutic knockdown to enhance cancer therapies should be considered." (PMID 34512157, 2021). "Nuclear Paraspeckle Assembly Transcript 1 (NEAT1) is another lncRNA that is overexpressed in various cancers, including OC." (PMID 34680193, 2021). "NEAT1 contributes to various biological processes and regulates diverse signaling pathways, especially in cancers." (PMID 34769497, 2021). "Literature has also shown that NEAT1 can augment tumorigenesis by regulating cancer‐favorable transcriptome." (PMID 34459124, 2021). "NEAT1 promotes tumorigenesis and progression via enhancing malignant phenotypes of cancer cells including migration, invasion, proliferation, and chemoresistance." (PMID 34552925, 2021). "NEAT1 (nuclear paraspeckle assembly transcript 1) is an oncogenic long non-coding RNA (lncRNA) that facilitates tumorigenesis in multiple cancers." (PMID 33738254, 2021). "Mechanistically, overexpression of HDAC1 recovered the cancer-inhibiting effects of miR-524-5p mimic or NEAT1 silence by deacetylation of tensin homolog deleted on chromosome ten (PTEN) and inhibiting AKT signal pathway." (PMID 34837887, 2021). "NEAT1 also acts as an ceRNA inhibiting function of miR-211 which is down-regulated in cancer and considered a tumour-suppressor." (PMID 33807045, 2021). "A recent study identified FTX as an oncogenic factor in GBM that increases during radiation exposure together with NEAT1, and both these lncRNAs are involved in cancer radio-resistance." (PMID 33066171, 2020). "NEAT1 (Nuclear paraspeckle assembly transcript 1) acts as a ceRNA involved in several types of cancer." (PMID 32760219, 2020). "The role of NEAT1 in expressing differentiation factors is especially important when considering cancer stem cells (CSCs)." (PMID 33143162, 2020). "This is consistent with several reports showing that NEAT1 promotes cancer progression by enhancing STAT3 signaling." (PMID 32843056, 2020).